RAB8B (RAB8B, member RAS oncogene family)
Description:
The small GTPases Rab are key regulators of intracellular membrane trafficking, from the formation of transport vesicles to their fusion with membranes. Rabs cycle between an inactive GDP-bound form and an active GTP-bound form that is able to recruit to membranes different sets of downstream effectors directly responsible for vesicle formation, movement, tethering and fusion (By similarity). RAB8B may be involved in polarized vesicular trafficking and neurotransmitter release (Probable). May participate in cell junction dynamics in Sertoli cells (By similarity). May also participate in the export of a subset of neosynthesized proteins through a Rab8-Rab10-Rab11-dependent endososomal export route.
Tractability: Antibody: UniProt places it where antibodies can reach, with high confidence; its Gene Ontology location is reachable by antibodies, with medium confidence. PROTAC: ubiquitination databases record sites on it; its protein half-life has been measured.
Gene: Protein-coding gene on chromosome 15 (63,189,560 to 63,267,776, forward strand). Ensembl gene ENSG00000166128.
Subcellular location: Cell membrane; Cytoplasmic vesicle, phagosome; Cytoplasmic vesicle, phagosome membrane; Endosome membrane
Pathways (Reactome):
Vesicle-mediated transport: RAB GEFs exchange GTP for GDP on RABs; TBC/RABGAPs
Metabolism of proteins: RAB geranylgeranylation
Gene Ontology:
Molecular function: GDP binding; protein binding; signaling receptor binding; GTPase activity; G protein activity; GTP binding; TPR domain binding
Biological process: antigen processing and presentation; cilium assembly; protein import into peroxisome membrane; cell-substrate junction organization; endocytic recycling; exocytosis; positive regulation of cell projection organization; positive regulation of corticotropin secretion
Cellular component: endosome membrane; extracellular exosome; peroxisomal membrane; phagocytic vesicle; endosome; plasma membrane; recycling endosome membrane; synaptic vesicle; trans-Golgi network transport vesicle; cell tip; perinuclear region of cytoplasm; phagocytic vesicle membrane; presynapse; recycling endosome
Genetic constraint (gnomAD): Loss-of-function variants: 7 observed, 16.48 expected, observed/expected ratio (o/e) 0.42, 90% interval 0.24 to 0.8. The upper end of that interval is the gene's LOEUF score, 0.8, which puts it in group 3 of 6, group 1 being the genes least tolerant of losing a copy. Missense variants: 125 observed, 175.94 expected, observed/expected ratio (o/e) 0.71, 90% interval 0.61 to 0.82. Synonymous variants: 76 observed, 69.55 expected, observed/expected ratio (o/e) 1.09, 90% interval 0.91 to 1.32.
Homologues: Orthologues: chimpanzee RAB8B (100% identical), rabbit RAB8B (99% identical), dog RAB8B (99% identical), mouse Rab8b (99% identical), rat Rab8b (99% identical), guinea pig RAB8B (96% identical), tropical clawed frog rab8b (95% identical), zebrafish rab8b (94% identical), macaque RAB8B (89% identical), Drosophila melanogaster Rab8 (79% identical), Caenorhabditis elegans rab-8 (75% identical), pig RAB8B (66% identical). Paralogues in human: RAB8A (84% identical), RAB10 (67% identical), RAB13 (65% identical), RAB1A (54% identical), RAB1B (53% identical), RAB26 (48% identical), RAB35 (48% identical), RAB37 (48% identical), RAB3A (48% identical), RAB3C (47% identical), RAB3B (46% identical), RAB3D (46% identical), and 56 more.
Diseases named in the same sentence as RAB8B in open-access papers:
RAB8B is named in the same sentence as 14 diseases in open-access papers, as found by Europe PMC text mining. Sharing a sentence is not in itself a finding about the gene and the disease. The quoted sentences say what the papers report.
celiac disease (1 paper, 2025). An autoimmune genetic disorder with an unknown pattern of inheritance that primarily affects the digestive tract. "Diabetics and celiac disease patients develop antibodies against RAB8B, and diabetic patient serum stimulates mesenchymal cell RAB8B expression, indicating that high levels of RAB8B potentially trigger vicious autoinflammatory and cytotoxic cycles." (PMID 40649110, 2025).
ciliopathies (1 paper, 2014). "From these observations, and the absence of cysts in the kidney and retinal degeneration, both of which are hallmarks of some ciliopathies, we concluded that Rab8a and Rab8b are not sufficient for the formation of cilia, at least during the lifespan of the DKO mice." (PMID 24213529, 2014).
COVID-19 (1 paper, 2026). A disease caused by infection with severe acute respiratory syndrome coronavirus 2. "This study defines robust consensus signatures and positions RAB8B as a critical host factor and potential therapeutic target in severe COVID-19." (PMID 42015392, 2026).
hearing loss (1 paper, 2020). "Earlier studies confirmed that Rab8b is an interacting partner of Otoferlin, which is a protein associated to hearing loss." (PMID 33101391, 2020).
metastatic tumor (1 paper, 2017).
schizophrenia (1 paper, 2025). A major psychotic disorder characterized by abnormalities in the perception or expression of reality. "The Rab GDP dissociation inhibitor-β (RAB8B, UniProt ID: P50395) is encoded by the RAB8B gene, whose gain-of-function variant enhancing RAB8B protein levels increases schizophrenia risk." (PMID 40649110, 2025).
infection (6 papers, 2017 to 2024). The state of being infected such as from the introduction of a foreign agent such as serum, vaccine, antigenic substance or organism. "We selected Rab5b, Rab11b, Rab8b and Rab11FIP1 for further characterisation in response to a ΔsdhA infection." (PMID 32096265, 2020). "We next confirmed, increase in RAB8B shorter transcript expression correlated with a decline in RAB8B protein level in MDMs upon H37Rv infection." (PMID 28257432, 2017). "We were able to achieve more than 70% transduction of long and short RAB8B transcripts as well as vector controls in THP-1 macrophages at the time of infection as well as 48 hours post-infection." (PMID 28257432, 2017). "In fact, in the second donor, longer RAB8B transcript increased manifold upon H37Ra infection, suggesting strong phagosome maturation flux in that individual." (PMID 28257432, 2017). "While H37Ra showed nearly 36% co-localization with RAB8B, it was significantly lower (22%) in the case of H37Rv infections." (PMID 28257432, 2017). "Even with a very limited analysis of RAB8B AS upon H37Rv infection in macrophages from two different donors, it was evident that there is an enormous possibility of inter-individual variations in the patterns of splicing." (PMID 28257432, 2017). "We further verified that selective RAB8B splicing influenced the outcome of infection, confirming it to be a true macrophage response." (PMID 28257432, 2017). "Similarly, infection by Mycobacterium tuberculosis (H37Rv strain) induced AS of RAB8B, a protein involved in intracellular vesicle transport, which helps the survival of H37Rv in THP1-infected macrophages." (PMID 38495873, 2024). "Our studies with RAB8B isoforms in regulating cellular responses to infection were quite revealing." (PMID 28257432, 2017). "While both the donors show a similar increase in RAB8B truncated transcripts upon H37Rv infection, one of them also showed an increase in truncated RAB8B upon H37Ra infection, however levels in H37Ra infected MDMs were always lower than those in H37Rv infected ones." (PMID 28257432, 2017). "Similarly, upon RAB8B knockdown bacterial co-localization to lysosome declined, which was again more pronounced and significant in the case of H37Ra infection compared to H37Rv infection." (PMID 28257432, 2017). "Thus infection induced alternate splicing of RAB8B is a specific response of macrophage, which helps the survival of virulent strain in the infected macrophages." (PMID 28257432, 2017). "We compared recruitment of RAB8B to GFP-expressing H37Ra and H37Rv phagosomes in THP-1 macrophages at 48 hours post-infection." (PMID 28257432, 2017). "At the gene level, expression of RAB8B, ACSL1 and Dynamin-1 was minimum in case of uninfected macrophages, intermediate in case of H37Ra infection and highest in the case of H37Rv infection." (PMID 28257432, 2017). "In macrophages derived from peripheral blood of healthy donors (MDMs), we could confirm infection specific alterations in the expression of IL1B, ACSL1, ATG13 and RAB8B isoforms as noted in THP-1 macrophages." (PMID 28257432, 2017). "It was, therefore, important to test that truncation of RAB8B transcript upon H37Rv infection was not a consequence of the transformed phenotype of THP-1 cells, a leukemic cell line, rather represented a true macrophage response upon bacterial infection." (PMID 28257432, 2017).
cancer (3 papers, 2017 to 2024). A tumor composed of atypical neoplastic, often pleomorphic cells that invade other tissues. "Chemotherapeutic agents stimulate the secretion and recycling of ABCB1-enriched EVs through the dysregulation of Rab8B and Rab5, leading to a significant increase of ABCB1 intercellular transfer, thus assisting sensitive cancer cells to develop an urgent resistant phenotype." (PMID 31830995, 2019). "CQ also induced Rab8b in normal human cells but not in cancer cells." (PMID 28076793, 2017).
tumor (2 papers, 2019 to 2025). "In the female cohorts, the downregulated proteins, such as utrophin, Rab-8B, and eS8, were associated with protein synthesis, while many upregulated proteins were linked to tumor progression." (PMID 41154628, 2025). "Very little is known about the role and mechanism of Rab8B in tumor cells." (PMID 31830995, 2019).
RAB8B also shares sentences with these, for which no sentence is quoted: bacterial infection (1 paper); parasitic diseases (1); Parkinson disease (1); retinal degeneration (1); tuberculosis (1).